INS (insulin)
Diseases named in the same sentence as INS in open-access papers (continued):
Sharing a sentence is not in itself a finding about the gene and the disease.
type 2 diabetes (continued). "Type 2 diabetes is a chronic metabolic disease characterized by inefficient use of insulin produced by the body (as opposed to type 1 diabetes, whereby insulin production is impaired due to damage to the beta cells of the pancreas, among other things)." (PMID 40901288, 2025). "Herein, we examined the following: 1) metabolic clearance rate of insulin (MCRI) in youth with obesity and normal glucose tolerance (NGT) versus those with IGT versus those with type 2 diabetes; 2) racial and ethnic differences in insulin dynamics; and 3) metabolic/adiposity correlates of MCRI." (PMID 40470991, 2025). "Type 2 diabetes mellites (T2DM), which is a chronic metabolic disease, is the most prevalent kind of diabetes and is characterized by abnormalities in insulin production and action, either of which may predominate." (PMID 39942422, 2025). "Some studies in smaller cohorts suggest that exercise training does not improve the insulin-suppressive effect on plasma BCAAs in overweight/obesity or type 2 diabetes." (PMID 40404819, 2025). "We did not assess concerns about reimbursement since all insulin-treated patients with type 2 diabetes in VA are eligible for CGM, and reimbursement is not a barrier to use." (PMID 40057678, 2025). "In a further analysis, we analysed the mean change in HbA1c from baseline to 6, 12 and 24 months after the isCGM index date for adults with type 2 diabetes and suboptimal glucose management, treated with MDI (T2D-MDI) or with basal insulin only (T2D-B), compared with prior use of BGM only." (PMID 39460755, 2025). "This is evident as most of these patients have short-duration type 2 diabetes and are not receiving insulin treatment." (PMID 39160371, 2025). "An 8-week training study using a combination of two non-weight-bearing HIIT modalities, rowing and cycling, demonstrated significant increases in insulin sensitivity in obese men with and without type 2 diabetes." (PMID 40247924, 2025). "The RABBIT-2 trial showed that a basal-bolus insulin regimen improved glycemic control compared to sliding-scale insulin (SSI) in non-critical patients with type 2 diabetes, achieving mean glucose levels of 166 versus 193 mg/dL." (PMID 39939862, 2025). "When considering all measures, fasting and insulin-stimulated, pre and post HIIT, plasma BCAAs were significantly higher in individuals with type 2 diabetes compared with glucose-tolerant individuals with obesity and lean control individuals (main effect p<0.001)." (PMID 40404819, 2025). "Acute exercise slightly reduced plasma BCAAs in both individuals with type 2 diabetes and individuals with obesity but did not potentiate insulin’s ability to reduce plasma BCAAs (study II)." (PMID 40404819, 2025). "Type 2 diabetes mellitus (T2DM) is a chronic condition, due to a non-autoimmune progressive loss of adequate β-cell insulin secretion, frequently against a background of insulin resistance and metabolic syndrome (MetS)." (PMID 40137087, 2025). "This indicates that the nervous system’s ability to suppress glucagon secretion in a manner independent of insulin during the fed state in healthy individuals is lacking in type 2 diabetes." (PMID 40940782, 2025). "Several randomized controlled studies involving human subjects investigated oral carnosine supplementation effects on blood glucose and fasting insulin in overweight non-diabetic, pre-diabetic, and type 2 diabetes (T2D) adults." (PMID 41008974, 2025). "The pathophysiological phenotype results from deficiency of almost all Nrf1 isoforms in mouse islets and MIN6 β-cells, leading to a marked increase in basal insulin release with reduced GSIS; this was viewed as a β-cell phenotype reminiscent of the early stage of type-2 diabetes." (PMID 40703332, 2025). "Unlike classic type 1 or type 2 diabetes, MODY is caused by mutations in genes involved in pancreatic beta-cell development, glucose sensing, or insulin secretion." (PMID 40777711, 2025).
type 2 diabetes (continued). "In insulin-resistant individuals and patients with type 2 diabetes, NR did not improve insulin sensitivity or glycemic control." (PMID 41300302, 2025). "Our main findings showed that insulin markedly suppressed plasma BCAAs in all examined groups, and that this effect was impaired in type 2 diabetes but not in obesity." (PMID 40404819, 2025). "There are several signaling pathways related to hypoglycemia, such as the HIF-1 signaling pathway, insulin signaling pathway, PI3K-Akt signaling pathway (PI3K-Akt signaling pathway), insulin resistance, AMPK signaling pathway, and type II diabetes mellitus (type II diabetes)." (PMID 41189218, 2025). "In CKD and type 2 diabetes, canagliflozin reduces insulin use with consistent effects regardless of baseline kidney function." (PMID 40036884, 2025). "The patient had type 2 diabetes managed with long-term insulin and no history of DPP-4 inhibitor use." (PMID 41019039, 2025). "Insulin is prescribed for individuals with type 1 diabetes and for those with type 2 diabetes who exhibit insulinopenia and do not respond adequately to dietary therapy or oral hypoglycaemic agents." (PMID 40747308, 2025). "The most common type is type 2 diabetes, usually in adults, which occurs when the body becomes resistant to insulin or does not produce enough insulin." (PMID 40351311, 2025). "Whereas overtly impaired insulin sensitivity, as evidenced by elevated HbA1c or a diagnosis of type 2 diabetes, was an exclusion criterion in the current study, no consideration was given to variations within the normal range." (PMID 40217385, 2025). "For example, studies involving patients with type 2 diabetes often report smaller weight reductions comparing with non-diabetic individuals, likely due to insulin resistance and differences in metabolic regulation." (PMID 40747302, 2025). "In particular, real-time insulin dosing for patients with type 1 and type 2 diabetes is a notable application." (PMID 40406780, 2025). "Management of insulin allergy involves various strategies, including switching to an alternative insulin formulation or, in patients with type 2 diabetes, transitioning to non-insulin hypoglycemic agents." (PMID 40869188, 2025). "In this study, we assessed the differences in glycemic status and insulin doses between non-ICU patients with type 2 diabetes monitored by POC or CGM during hospitalization on a day-to-day basis and during day, evening, and night shifts." (PMID 40980547, 2025). "The cephalic phase of insulin secretion is absent in type 2 diabetes, and glucagon secretion is not suppressed after eating." (PMID 40940782, 2025). "Type 1 diabetes was formerly known as juvenile or insulin-dependent diabetes mellitus (IDDM), while type 2 diabetes (T2DM) is a chronic condition in which the pancreas produces little to no insulin." (PMID 40621264, 2025). "Still, research suggests that it may be an effective strategy for treating metabolic disorders, type 2 diabetes mellitus (T2DM), obesity, and non-alcoholic fatty liver disease, primarily by reducing fat accumulation and inhibiting postprandial insulin secretion." (PMID 41377049, 2025). "Moreover, network pharmacology study involve common targets of bergaptol and type 2 diabetes, which was further applied for gene ontology suggested INSR, NF-κB, Akt and GSK-3β targets for the insulin signalling and resistance both." (PMID 40126146, 2025). "Third, the health checkup data analyzed in the present study did not contain data on insulin, race, family health history, and accurate diagnosis including discrimination between type 1 and type 2 diabetes as well as more detailed stratification." (PMID 40395818, 2025). "In contrast to humans, dogs do not develop type 2 diabetes but can develop glucose intolerance in relation to obesity, and as such, are almost always insulin-dependent." (PMID 40051530, 2025).
type 2 diabetes (continued). "Diabetes mellitus is a non-communicable disease, which is characterized by the absence of (type 1 diabetes, T1D) or insensitivity to (type 2 diabetes, T2D) insulin, a major regulator of blood glucose concentrations." (PMID 41244562, 2025). "Furthermore, C. verum and inulin significantly decreased weight, BMI, serum insulin, HOMA index, lipaemic pattern, TC, TG, and LDL in patients with metabolic syndrome and type-2 diabetes or impaired glucose tolerance." (PMID 40343290, 2025). "It is common that patients with mitochondrial diseases and type 2 diabetes need insulin therapy, while in non-insulin-dependent patients sulphonylureas are the first-choice pharmacological treatment." (PMID 41480351, 2025). "Even the removal of 10 kg of abdominal subcutaneous AT by liposuction (equal to 20% reduction in total body fat mass) did not affect insulin sensitivity or parameters of glucose and lipid metabolism in women with obesity with or without type 2 diabetes." (PMID 40069923, 2025). "Unlike metformin, Imeglimin also restored insulin secretion and reduced β-cell apoptosis, supporting its role in preserving β-cell function in type 2 diabetes." (PMID 40822946, 2025). "In cases of type 2 diabetes, insulin therapy is recommended if glycemic targets are not met following a three-month regimen combining lifestyle interventions and oral hypoglycemic agents." (PMID 40900896, 2025). "Can an artificial intelligence–based insulin clinical decision support system for type 2 diabetes achieve glycemic outcomes that are not inferior to standard therapy administered by senior endocrinology physicians?" (PMID 40332936, 2025). "Nevertheless, rosiglitazone,a PPARγ agonist that can improve insulin sensitivity and glycemic control inpatients with type 2 diabetes, was found to increase PON1 activity, although therewas no significant change in the serum PON1 concentration." (PMID 40834279, 2025). "However, in type 2 diabetes, both GLP-1 secretion and activity are impaired, leading to insufficient insulin release and excessive glucagon levels, which exacerbate glucose dysregulation." (PMID 40260393, 2025). "The current therapeutics for the management of type 2 diabetes (T2D) include medications prescribed either in the presence or absence of exogenous insulin." (PMID 41011279, 2025). "In mice models of primary obesity and type 2 diabetes, a 16-week ADF intervention significantly reduced blood glucose levels and preserved pancreatic β-cell function by modulating the hepatic AMPK/mTOR axis, thus effectively countering insulin resistance." (PMID 41536827, 2025). "The most widely prescribed medications for type 2 diabetes (T2DM) (sitagliptin, exenatide, insulin glargine, dulaglutide, canagliflozin, and liraglutide) were compared with semaglutide administered either alone or combined with insulin, metformin, sulfonylurea, and/or insulin." (PMID 40872522, 2025). "Prior to HIIT, the ability of insulin to suppress plasma BCAAs was reduced in individuals with type 2 diabetes compared with lean individuals (p=0.048), but not individuals with obesity (p=0.168)." (PMID 40404819, 2025). "Type 2 diabetes results from failing β-cell function, and the body’s cells do not effectively respond to insulin." (PMID 40091018, 2025). "Glucagon-like peptide-1 receptor agonists (GLP-1RAs) are established treatments for type 2 diabetes mellitus (T2DM), improving glycaemic control through multiple mechanisms, including enhanced insulin secretion, delayed gastric emptying, and appetite suppression." (PMID 41516966, 2025). "Type 2 diabetes is due to a lack of insulin action with secondary impairment in glucose transport and utilization in insulin-sensitive tissue (e.g., striated muscle and adipose tissue)." (PMID 41295303, 2025). "In Type 2 diabetes, the body either becomes insulin resistant or the pancreas fails to secrete sufficient insulin." (PMID 40385838, 2025).
type 2 diabetes (continued). "In contrast, there are no established guidelines for testing frequency in non-insulin-treated type 2 diabetes patients." (PMID 41458677, 2025). "This single-center, prospective observational cohort study enrolled 191 patients with type 2 diabetes and early-stage DKD, who were stratified into three groups based on treatment regimen: control group (n = 63), insulin group (n = 71), and GLP-1RA group (n = 57)." (PMID 40496556, 2025). "Type 2 diabetes occurs when the pancreas does not secrete enough insulin, and the body’s cells do not effectively respond to the insulin secreted." (PMID 40671915, 2025). "Recently, more studies have explored the benefits of CGM among people with type 2 diabetes not using insulin." (PMID 40851538, 2025). "The use of CGM has been identified as a beneficial tool for individuals with type 2 diabetes who are not using insulin to achieve certain glycemic goals." (PMID 41413776, 2025). "The latest Standards of Care 2025 from the ADA recommend the use of CGM as beneficial for improving glycemic control, not only in individuals with type 2 diabetes who use insulin, but also in those who do not use insulin." (PMID 41157216, 2025). "A 17-year-old male American Ecuadorian patient, with a paternal history of type 2 diabetes presented with hyperglycemia without ketoacidosis at 8 years, when he was diagnosed with type T1D and was started on intermediate acting insulin NPH with poor adherence." (PMID 41020216, 2025). "Although acute exercise reduces fasting BCAA levels, neither acute exercise nor exercise training affects insulin’s ability to suppress plasma BCAAs in glucose-tolerant individuals with or without obesity or in individuals with type 2 diabetes." (PMID 40404819, 2025). "Still, the importance of glycemic management is proven, even when most participants (>85%) were treated without insulin, although the effects of glycemic management have been controversial, especially in type 2 diabetes, in previous trials." (PMID 41129145, 2025). "By enhancing insulin sensitivity, regulating lipid metabolism, and protecting against cardiac remodeling, NRG4 represents a promising therapeutic target in addressing heart disease, particularly in populations affected by obesity and type 2 diabetes." (PMID 40149686, 2025). "We found that PHD2 levels were significantly positively correlated with visceral adipose tissue (VAT via computed tomography), body mass index (BMI, kg/m2), blood markers for type 2 diabetes, HBA1C and insulin, triglycerides and the metabolic syndrome (MetS; odds ratio 1.22)." (PMID 39209825, 2024). "Peroxisome proliferator-activated receptor γ (PPARγ), a target of thiazolidinediones used to treat patients with type 2 diabetes mellitus (T2DM), plays a crucial role in enhancing insulin sensitivity, promoting adipogenesis and exerting anti-inflammatory effects." (PMID 39431155, 2024). "The results showed that consuming pure anthocyanins or anthocyanin-rich meals did not have a significant impact on serum insulin levels while significantly reducing the HOMA-IR index in individuals with type 2 diabetes and those who were overweight or obese." (PMID 38892607, 2024). "Unlike autoimmune type 1 diabetes, which requires insulin and usually strikes in childhood or adolescence, type 2 diabetes can be controlled with lifestyle changes and medication." (PMID 39867544, 2024). "Thus, many adults with type 2 diabetes (T2D) eventually require and benefit from insulin therapy." (PMID 38767675, 2024). "We report an 18-year-old female who presented with symptoms of type 2 diabetes with non-ketotic hyperglycemia, and tested positive for multiple islet cell autoantibodies but did not require insulin therapy at diagnosis." (PMID 39329041, 2024). "In type 2 diabetes islets, miR-200c expression increases, leading to reduced glucose-stimulated insulin secretion in EndoC-βH1 cells compared with non-diabetic donors." (PMID 38805166, 2024).
type 2 diabetes (continued). "Type 2 diabetes mellitus (T2DM) is characterized by hyperglycaemia and abnormal insulin secretion." (PMID 38332532, 2024). "Studies have demonstrated that mice with Imp2 deletion in mesenchymal stem cells (MSCs) exhibit resistance to diet-induced obesity without impairments in glucose and insulin tolerance, ultimately protecting against the development of type 2 diabetes (T2D)." (PMID 39596216, 2024). "The most common variety is type 2 diabetes (t2DM), usually found in adults, which occurs when the body becomes resistant to insulin or does not make enough insulin." (PMID 38676064, 2024). "Patients usually present over the age of 30 years with symptoms suggestive of type 2 diabetes and test positive for islet cell antibodies, but do not require insulin therapy at diagnosis and for up to six months thereafter." (PMID 39329041, 2024). "Smoking cessation remained predictive of a lower incidence of HF, regardless of the duration of type 2 diabetes, number of oral antidiabetic agents, and use of insulin." (PMID 38198206, 2024). "Current treatment for the management of type 2 diabetes includes lifestyle changes and medications including metformin, sulfonylureas, glinides, thiazolidinediones, GLP-1 agonists, DPP-4 inhibitors, SGLT-2 inhibitors, and insulin analogs." (PMID 39149678, 2024). "Unlike cases of type I diabetes where the individual does not produce an adequate amount of insulin, individuals with type 2 diabetes (T2D) do not effectively respond to the insulin produced." (PMID 38767782, 2024). "In contrast, respondents with type 1 diabetes (OR = 2.46; p = 0.010) and respondents receiving insulin therapy (OR = 1.96; p = 0.001) participated more frequently in DSME than those with type 2 diabetes and without insulin therapy." (PMID 39264968, 2024). "In a separate experiment conducted on Type 2 Diabetes Mellitus (T2D) human donor alpha cells, the results demonstrated that glucagon exocytosis is not prevented by hyperglycemia or insulin inhibition." (PMID 39594662, 2024). "Exposure to roxadustat led to a reduction in insulin-stimulated phosphorylation of Akt-Ser473 and GSK3β-Ser9, and an increase in insulin-stimulated phosphorylation of AS160-Thr642 in myotubes from donors with type 2 diabetes." (PMID 38814443, 2024). "The findings of this study support the integration of structured educational programs into standard care practices for type 2 diabetes, particularly for patients with HbA1c levels greater than 7% who are not receiving insulin treatment." (PMID 39639901, 2024). "They present in the same way, that is, with symptoms of type 2 diabetes, test positive for islet cell autoantibodies, and again do not require insulin therapy at diagnosis and for six months afterward." (PMID 39329041, 2024). "Such alternative approaches could include optimizing insulin dose titration or exploring the use of SGLT-2 inhibitors or GLP-1 agonists, which have demonstrated efficacy in the management of type 2 diabetes." (PMID 39131791, 2024). "The analysis started at the diagnosis of cancer for the cases and only include individuals with type 2 diabetes with no insulin treatment at that time." (PMID 39020360, 2024). "Patients aged ≥ 40 years, diagnosed with type 2 diabetes, having stable non-insulin GLA use, and without NAFLD/NASH history were included." (PMID 39420429, 2024). "The lack of differences between groups with/without obesity/type 2 diabetes needs to be considered in the light of our limited sample size, multiple comparisons and differences in prevailing circulating concentrations of insulin." (PMID 38276866, 2024). "Type I diabetes, or insulin-dependent diabetes, occurs when the pancreas is unable to secrete insulin, and type II diabetes, or non-insulin-dependent diabetes, occurs when there is an imbalance between the absorption of blood sugar and insulin secretion." (PMID 39421675, 2024).